G6PD (glucose-6-phosphate dehydrogenase)
Diseases named in the same sentence as G6PD in open-access papers (continued):
Sharing a sentence is not in itself a finding about the gene and the disease.
malaria (continued). "More recently, a large multi-centre cases-control study of severe malaria involving 12,000 cases and 17,000 controls demonstrated a highly significant association of G6PD-202 with risk of severe malarial anaemia while a small but significant protection with cerebral malaria." (PMID 25885177, 2015). "Establishing whether malaria patients are G6PD deficient is also important because of the potential use of 8-aminoquinoline drugs (e g, primaquine and its derivatives) for malaria elimination in sub-Saharan Africa." (PMID 25671784, 2015). "In summary, through a much better understanding of the true extent of genetic diversity within and around the G6PD locus, we have identified alleles associated with protection from severe malaria in Tanzania, driven by a balancing heterozygous advantage mechanism." (PMID 25671784, 2015). "Numerous genetic variants of G6PD, residing in the X chromosome, are found among African populations: mutations causing A- deficiency can lead to serious clinical outcomes (including hemolytic anemia) but also confer protection against severe malaria." (PMID 25671784, 2015). "The disease has also exerted significant selection pressure on the human genome, as evidenced by the congruence of malaria parasite prevalence with sickle cell trait (HbAS) and other hemoglobinopathies, such as thalassemias and glucose-6-phosphate dehydrogenase (G6PD) deficiency." (PMID 25805752, 2015). "Considering that the national standard of malaria treatment in the country includes primaquine, further research is necessary to ascertain the risk of PQ-triggered haemolytic reactions in sectors of the population more likely to carry G6PD mutations." (PMID 26249834, 2015). "The high frequency of the G6PD A− variant among malaria patients in Honduras lends support to the well-known hypothesis correlating their geographical distribution." (PMID 26249834, 2015). "Our study provides strong support for the conclusion that the G6PD c.202T allele has reached its present frequencies in much of sub-Saharan Africa through positive selection for heterozygous girls through a mechanism mediated by malaria." (PMID 26686045, 2015). "G6PD-deficiency is important in malaria, as certain anti-malarial drugs could induce haemolysis in such patients and mutations in this gene may influence the susceptibility or resistance to the disease." (PMID 25885177, 2015). "A number of polymorphic markers for G6PD have been described and used to explore the evolution of the gene in various contexts, and the abnormal functional variants thought to offer protection against malaria in particular." (PMID 24586352, 2014). "The association of G6PD phenotype with sex, ethnic group and malaria smear positivity was tested." (PMID 25406667, 2014). "The strongest evidence implicating G6PD deficiency in malaria protection would ideally be consistent with an additive genetic model, with hemizygous males and homozygous females exhibiting similar clinical phenotypes, and heterozygous females displaying intermediate phenotypes." (PMID 25201310, 2014). "Similarly among females, children who were G6PD deficient were more likely to contract malaria as compared to G6PD normal children (adjusted OR = 2.68, 95% CI: 1.10–6.52, p = 0.031)." (PMID 25470251, 2014). "The 202A/376G G6PD A-allele is considered to be the most common G6PD deficiency allele in sub-Saharan Africa, though incidence and prevalence of malaria have continued to be high in this region yet known to confer protection against malaria." (PMID 25202468, 2014). "Some studies have concluded that G6PD deficiency confers resistance to malaria." (PMID 24943486, 2014). "The techniques used to identify G6PD-deficient individuals are important, as demonstrated by a recent study observing uncomplicated malaria protection only when characterizing deficiency using enzymatic activity from biochemical assays, but not genotyping of G6PD202." (PMID 25015414, 2014).
malaria (continued). "Establishing whether malaria patients are G6PD deficient is important, because of the future need to use 8-aminoquinolines (e.g., primaquine (PQ) and its derivatives) for malaria elimination in sub-Saharan Africa." (PMID 25015414, 2014). "A study was proposed, which would involve the recruitment of people, some of whom would be likely to have a glucose-6-phosphate dehydrogenase (G6PD) deficiency: a common hereditary condition that protects against malaria but also predisposes towards haemolysis." (PMID 24533875, 2014). "The findings on differences in prevalence is not consistent with the a similar study conducted in Gabon that showed that female heterozygous children were protected against asymptomatic malaria with rates of 39% versus 67% (p = 0.03) compared to those with wild type G6PD alleles." (PMID 24943486, 2014). "High malaria parasitaemia and mortality was observed among G6PD-deficient patients in Iran." (PMID 25406667, 2014). "G6PD-deficient individuals are at risk of haemolysis when exposed, among other agents, to primaquine and tafenoquine, which are capable of blocking malaria transmission by killing Plasmodium falciparum gametocytes and preventing Plasmodium vivax relapses by targeting hypnozoites." (PMID 25406667, 2014). "Geographical, epidemiological and in vitro evidence suggest the hypothesis that glucose-6-phosphate dehydrogenase (G6PD) deficiency confers protection from malaria disease caused by the Plasmodium falciparum parasite." (PMID 25015414, 2014). "Overall, the WST8 test has a considerable potential as a diagnostic tool prior to primaquine administration in malaria-endemic areas as a point of care test and/or as a screening tool for assessing G6PD prevalence in large-scale screening studies in areas contemplating primaquine deployment." (PMID 23782846, 2013). "The present study begins the task of characterizing G6PD variant spatial distribution and diversity, with the aim of contributing towards the evidence-based policies for primaquine treatment so essential to realizing the vision of malaria elimination." (PMID 24228846, 2013). "Similarly, we expected to see a reduced malaria risk with G6PD-202A (A- deficiency), as shown in another Malian population with similar allele frequencies in controls to our study." (PMID 22957039, 2012). "The main limitation to the use of primaquine, either for the radical cure of Plasmodium vivax or Plasmodium ovale malaria, or as a gametocytocide in Plasmodium falciparum malaria, is the risk of haemolysis in patients who are glucose 6-phosphate dehydrogenase (G6PD) deficient." (PMID 23237606, 2012). "The use of CDA for treating uncomplicated malaria may increase the risk of haemolytic anaemia in G6PD-deficient children." (PMID 22546009, 2012). "Finally, the researchers used data on the geographical occurrence of G6PD variants classified according to their enzyme activity levels as mild or severe to derive an index of hemolytic risk from G6PDd for each malaria-endemic country." (PMID 23152723, 2012). "Epidemiological and in vitro studies suggested that G6PD deficiency could confer a protection against P. falciparum infection by inhibiting erythrocyte invasion or intracellular development of the malaria parasite." (PMID 22546009, 2012). "Since the selection coefficient of the G6PD allele conferring resistance to malaria has been estimated to be more than 0.1, we may say that the LRH test has enough power to detect such a strong recent selection." (PMID 21909391, 2011). "In this case, the data presented may contribute to an explanation of the mechanism of malaria protection in G6PD deficient subjects." (PMID 21246053, 2011). "This association between G6PD and malaria was supported by population genetic analyses of the G6PD locus, which indicated that these mutations may have recently risen in frequency in certain geographic regions as a result of positive selection." (PMID 22171972, 2011).
malaria (continued). "Mutations in G6PD and Beta-globin have been hypothesized to provide a heterozygote advantage due to malaria resistance." (PMID 21901107, 2011). "In patients with malaria, higher than expected G6PD enzyme levels can occur in individuals with G6PD-deficient genotypes because the increased erythrocyte replacement rate results in a younger erythrocyte population and newly formed erythrocytes have a greater capacity for G6PD production." (PMID 21849081, 2011). "The ten common G6PD variants were investigated in dried blood spot samples collected from 317 Thai (84 males, 233 females) and 183 Burmese (11 males, 172 females) populations residing in malaria endemic areas of Thailand using PCR-RFLP method." (PMID 22171972, 2011). "In 1960, Allison and Motulsky first suggested that individuals deficient in G6PD might be at a selective advantage in malaria endemic areas." (PMID 20927393, 2010). "Thus, the implications of G6PD deficiencies unrelated to malaria represent a significant medical problem." (PMID 20927393, 2010). "The concordance of the distribution of G6PD deficiency with maps of historical malaria led to the hypothesis that the trait is protective against P. falciparum." (PMID 20520804, 2010). "The difference in historical malaria exposure between the two Kenyan sites has significantly increased the frequency of malaria protective alleles glucose-6-phoshpate dehydrogenase (G6PD) and Hemoglobin S (HbS) in the holoendemic site compared to the episodic transmission site." (PMID 19317913, 2009). "Interestingly, the significant association between malaria incidence and G6PD phenotype in females was lost when G6PD status was defined by G6PD genotype (RR = 0.99 for heterozygous/homozygous females compared to wild-type females)." (PMID 19789650, 2009). "We hypothesized that the initial infection rates would be similar for different genotypes, while the time to reach densities that cause symptomatic malaria would be longer for G6PD deficient individuals and individuals with α+-thalassaemia." (PMID 19460160, 2009). "To further explore the relationship between G6PD enzyme activity and the risk of malaria, we determined whether the degree of deficiency affected an individual's risk of malaria." (PMID 19789650, 2009). "Based on this observation, it was hypothesized that G6PD deficiency had arisen as a protective factor against lethal malaria." (PMID 19789650, 2009). "PQ may be associated to the risk of acute intravascular haemolysis when give to G6PD deficient patients One study found 12% prevalence in malaria patients in one endemic area of the pacific coast of Colombia." (PMID 17328806, 2007). "Malaria, thalassemia, and sickle cell anemia may, therefore, exert a positive selection pressure for carriers of G6PD mutations." (PMID 17637841, 2007). "G6PD levels also exhibited a substantial autosomal component, supporting the presence of other regulatory loci that may influence malaria susceptibility and resistance through regulation of G6PD levels." (PMID 16934002, 2006). "We found a substantial X-linked component influencing G6PD levels—a result that was expected, because mutations in the G6PD gene (Xq28) are relatively common in Sardinia where they reduce G6PD levels and protect against malaria." (PMID 16934002, 2006). "There is some concern that the application of MB could be followed by haemolysis in glucose-6-phosphate dehydrogenase (G6PD) deficient individuals in malaria-endemic regions." (PMID 16179085, 2005). "Additionally, we detect the G6PD Mediterranean variant in three Tylos-period Bahrainis and estimate that it rose to high frequencies in Eastern Arabia due to strong positive selection exerted by malaria endemicity coinciding with the appearance of agriculture." (PMID 38417441, 2024).
malaria (continued). "A study on barriers and facilitators for G6PD test implementation identified three main barriers: perceived low risk of haemolysis, wrong perception of P. vivax malaria as a benign condition, and the cost of routine testing as part of the healthcare attention of malaria patients." (PMID 39488711, 2024). "Furthermore, the geographical distribution of ABO blood groups, haemoglobin and G6PD genotypes are often associated with anaemia and malaria protection among certain ethnic groups, but their effect among iron-fortified infants and young children is unknown." (PMID 36959634, 2023). "However, there was a higher risk of malaria for children with G6PD A-A- in both groups." (PMID 36959634, 2023). "In addition, 66.7% (12/18) of G6PD deficient individuals were malaria positive." (PMID 36076204, 2022). "This suggests that AEOGL had an antioxidant impact when co-administered with primaquine and could be a candidate for the development of an antimalarial-medicinal plant combination regimen to treat malaria especially in sickle cell and G6PD-deficient patients prone to oxidative stress." (PMID 36399959, 2022). "When G6PD status was categorized according to an individual’s enzyme activity during follow up, two thirds of participants with severe deficiency and almost 90% of those with intermediate deficiency had normal enzyme activity (>70%) at the time of presentation with malaria." (PMID 35544453, 2022). "Similarly, glucose-6-phosphate dehydrogenase (G6PD) deficiency is one of the common enzymopathies affecting people living in regions where malaria is endemic, as a result of natural selection against genes that are associated with susceptibility to malaria." (PMID 35864541, 2022). "As such, appropriate methods for G6PD diagnostic testing at or near where patients seek care for malaria are essential to guide safe and effective management of P. vivax cases and increase the potential of these medications to support malaria control and elimination efforts." (PMID 34383774, 2021). "It is unclear whether G6pd deficiency causes more severe hemolysis at early stage in malaria." (PMID 34456927, 2021). "PQ radical cure is recommended in the antimalarial treatment guidelines of most malaria endemic countries, but in practice its prescription is often low, since policy makers and healthcare providers are reluctant to use it, primarily due to fears of toxicity in G6PD deficient patients." (PMID 33175835, 2020). "The “social life” of G6PD testing is understood as the making, assigning, and interpretation of meanings and rationality of this novel diagnostic tool amongst different actors including policy makers, malaria control program managers, health workers, patients, and community members." (PMID 33396538, 2020). "While this may indicate that the use of primaquine in the local population could be safer than initially evaluated, systematic G6PD deficiency testing will be necessary to successfully implement radical cure regimens for Pv and support future malaria elimination efforts." (PMID 32490754, 2020). "As with adult management of malaria, newborn screening with only qualitative G6PD tests will identify males who are most frequently at the highest risk of developing G6PD related complications in the early neonatal period but will miss G6PD intermediate females." (PMID 32766454, 2020). "Chemoprevention strategies for eradicating malaria, such as mass drug administration with primaquine to reduce the high reservoir of malaria infection, cannot be implemented in most malaria-endemic countries due to drug resistance and potential prevalence of glucose-6-phosphate deficiency (G6PD)." (PMID 31248414, 2019). "While considered an essential component for malaria elimination, the safety of PQ must be given careful consideration given the risk of hemolysis in G6PD-deficient individuals, who may be at even more risk in a large-scale elimination campaign that does not allow for close, individual follow-up." (PMID 30326952, 2018).
malaria (continued). "Circumstantial evidence suggests that G6PD deficiency imparts some resistance against malaria as evidenced by the overlap in the geographical distribution of the deficiency with present and past malaria endemicity, although the exact nature of such potential protection is unknown." (PMID 29558929, 2018). "Thus, coexistence of the G6PD deficiency and β-thalassaemia among the local population in Azerbaijan might contribute to the phenomenon of asymptomatic malaria in the country, which may account for the difficulty in eliminating malaria in this country." (PMID 30286752, 2018). "These include the polymorphisms for the following variants: G6PD A(−), Mediterranean, Seatle, Chatam, Santamaria, Betica-Selma, and other SNPs that were polymorphic in South America, according to the 1000 Genome data, and/or previously associated with protection to severe malaria." (PMID 28619120, 2017). "Although malaria was prevalent along the continent, from Russia and Scandinavia to Southern Europe, some resistance mutations such as G6PD B- are nowadays restricted to the Mediterranean, which suggests that the impact of the disease may have been different between European regions." (PMID 28469196, 2017). "In the presence of life threatening malaria, unfavourable lyonization may have provided an advantage for survival, thus selecting for such heterozygous females as revealed by the high numbers of G6PD deficient females observed in our study." (PMID 28152025, 2017). "Moreover, the endemicity of malaria means that drugs such as quinine, primaquine, and amodiaquine that predispose G6PD deficient to oxidant stress may be routinely prescribed to malaria patients." (PMID 29021902, 2017). "However, while there is information of some malaria-resistance alleles from Europe, notably from the Mediterranean area (such as the HBB and the G6PD variants), little is known about the magnitude of selection due to malaria in the continent because of the eradication of the parasite around 1950." (PMID 28469196, 2017). "Recognizing the uncertainty around the potentially complex G6PD allele inheritance in Madagascar, this study therefore aims to begin strengthening the evidence base of epidemiological data available to the Malagasy National Malaria Control Programme (NMCP) regarding G6PD deficiency." (PMID 28376871, 2017). "Therefore, the hemolytic toxicity of G6PD variants has an impact on malaria treatment." (PMID 28583873, 2017). "Moreover, there is a need to evaluate the effects of acute malaria on G6PD tests, since G6PD-deficient patients who have recently suffered hemolysis may have a normal G6PD test." (PMID 27430544, 2016). "Because the haemolytic risk of PQ-based regimens in malaria-endemic regions depends also on the severity of G6PD mutations involved in the deficiency, G6PD genetic testing could be useful when the benefits of PQ treatment outweigh the risk in patients living in these areas." (PMID 26753754, 2016). "In summary, this study identifies specific G6PD alleles that confer resistance to severe malaria in this population and reveals a potentially important role of female heterozygotes in maintaining the high frequency of G6PD polymorphisms in malaria endemic populations." (PMID 25671784, 2015). "Use of primaquine for malaria treatment may result in severe hemolysis in G6PD deficient patients." (PMID 26226515, 2015). "Amongst the approximately 190 genetic variants causing clinical deficiency of Glucose-6-phosphate dehydrogenase (G6PD) that have been characterised, the A- deficiency is the most common in sub-Saharan Africa populations, and is associated with protection from severe malaria." (PMID 25671784, 2015). "Moreover, P falciparum is the only significant cause of clinical malaria in Kenya; therefore, we were unable to investigate the hypothesis that G6PD deficiency might protect against Plasmodium vivax malaria." (PMID 26686045, 2015).